CD34 (CD34 molecule)
Diseases named in the same sentence as CD34 in open-access papers (continued):
Sharing a sentence is not in itself a finding about the gene and the disease.
tumor (continued). "Immunohistochemically, the tumor cells were widely positive for vimentin, CD56, CD99 and focally positive for synaptophysin, CD10, progesterone receptor, desmin and CD34, but negative for EMA, cytokeratin, estrogen receptor, S-100, GFAP and myoglobin." (PMID 23217062, 2012). "Immunohistochemically, the tumor cells were positive for KIT, negative for CD34, and negative or weakly positive for SMA, and the same result was observed for the highly aggressive tumor cells of the primary gastric lesion." (PMID 23227375, 2012). "In the study group 4, in the tumor-host interface of the 13 re-examined DCIS cases, 8 cases showed SMA positive, while 7 cases showed CD34 negative." (PMID 22067528, 2011). "The tumor cells were positive for EMA and S-100 protein and focally positive for cytokeratin and ER but negative for progesterone receptor, CD34, and CEA." (PMID 22332016, 2011). "All tumor cells showed strong positive reactivity for vimentin and negative reactivity for CD31, CD34, and myoglobin." (PMID 21329505, 2011). "Cells tumour was highly positive for vimentin and CD68 and negative for S100, factor XIIIa and CD34 and SMA." (PMID 20066060, 2009). "Cells tumour was highly positive for vimentin and CD68 and negative for S100, CD34, Factor XIIIa and SMA." (PMID 20066060, 2009). "The tumor tissues showed a positive reaction for CD117, CD34 and vimentin, but not for desmin, PLAP, S-100, SM-actin, NF, GFAP, NSE, HMB-45, and SC-actin." (PMID 19500398, 2009). "Immunohistochemical analysis showed that the tumour cells expressed vimentin, but not smooth-muscle actin (SMA), CD34, or desmin." (PMID 18257933, 2008). "Nevertheless, CD34 or CD31 is prefered to visualise blood vessels in solid tumours, as FVIII expression is absent in some tumour capillaries that can lead to underestimation of the presence and extent of BVI." (PMID 16670715, 2006). "Immunohistochemical staining was performed and tumor cells were positive for CD31, CD34, and vimentin, whereas negative for factor antigen, CD117, and S-100." (PMID 16159405, 2005). "The two sets of vasculature are thought to be functional in supporting tumour development, so why is the MVD recognised by Mab to CD105, but not by Mab to CD34, correlated with prognosis?" (PMID 12778073, 2003). "Moreover, the tumor was partly positive for S-100P, CD56, CD68 and LCA, while negative for chromogranin A, synaptophysin, Myo D1, CD34, calretinin and BCOR." (PMID 39930783, 2025). "The tumor cells were negative for SMA, CD34, bcl-2, ALK, and BCOR." (PMID 39857780, 2025). "Moreover, by immunohistochemistry (IHC), the tumor showed diffuse reactivity for vascular markers, including ERG, CD31, CD34, and D2-40, as well as for TFE3, while being negative for MUC4, CAMTA1, smooth-muscle actin, desmin, S100 and keratins." (PMID 40879254, 2025). "However, CD34 is not a specific immunomarker of SFT and it can be negative in about 10% of SFTs, furthermore, CD99 and BCL2 are usually expressed in many other neoplasms." (PMID 40027129, 2025). "IHC staining further confirmed tumor's smooth muscle and mesenchymal origins, with positive for vimentin, smooth muscle antibody (SMA), synapsin (Syn), actin, desmin, CD34 (vascular), while negative for and chromogranin A (CgA)." (PMID 39776317, 2025). "Immunohistochemically, tumor cells express glial markers (i.e., GFAP and OLIG2) and CD34, which may be patchy or diffuse and may also display non-neoplastic ramified neural elements in the associated cerebral cortex." (PMID 38544524, 2024). "Interestingly, vascular markers CD31, CD34 and ERG highlighted a dense capillar network between tumour nests, without staining of tumour cells, which ruled out an endothelial origin such as angiosarcoma or littoral cell angioma." (PMID 38643139, 2024).
tumor (continued). "However, in our practice, we found that the tumor tissue of AP-DFSP on frozen sections is not well differentiated from normal tissue, so it is recommended to make routine paraffin sections and add a CD34 marker to distinguish them." (PMID 39634408, 2024). "Immunohistochemistry of these tumor cells was negative for STAT-6, CD34, SMA, and S-100." (PMID 39432588, 2024). "The tumor cells do not express Bcl-2, CD99, or CD34, which is beneficial for differentiation." (PMID 39206171, 2024). "The tumor cells were EMA, LCA, actin, CD34, CKAE1/AE3, S-100, NSE, and SOX-10 negative." (PMID 37469410, 2023). "The neoplasm showed positivity for Smooth Muscle Actin, MDM2 (focally), and pan-TRK, while Caldesmon, CD31, CK AE1/AE3, Desmin, ERG, S100, SATB2, STAT6, H3F3A (G34V), H3F3A (G34W), H3F3A (G34R), SS18-SSX, SSX, STAT6, and CD34 were negative." (PMID 37876963, 2023). "However, one study reported tube formation ability and lack of CD31 and CD34 expression, and concluded that cells were undergoing VM, when the TFA was performed using GSCs isolated from patient tumours grown in EGM." (PMID 36823554, 2023). "The tumor cells were negative for AE1/3, Cam5.2, CKIT, DOG1, CD99, SOX10, S100, HMB45, MelanA, Syn, CgA, Trypsin, Desmin, SMA, Caldesmon, collagen type 4, Laminin, Inhibin, Calretinin, STAT6, CD34, ERG, WT1, ER, PR, and SALL4." (PMID 36928336, 2023). "Additional studies of biomarkers showed the tumor was negative for EBV by EBER in situ hybridization, had patchy positivity for p16 with 40% positive tumor cells, and was positive for CK5/6, p40, and CD34 immunostains." (PMID 37397571, 2023). "The tumor was positive for CD117, Vim, CD56 and NSE and showed focal expression of desmin but was negative for myogenin, S-100, SYN, INSM1, CD34, STAT6, INI-1, Brachyury, ERG, TLE1, AE1/AE3, WT-1, CD99 and SMA." (PMID 35488288, 2022). "Immunohistochemically, tumor cells were positive for estrogen receptors (ER), progesterone receptors (PR), and focally for smooth muscle actin (SMA), while negative for calretinin, CD34, desmin, and S-100 protein." (PMID 35860056, 2022). "Histologically, a cellular tumor comprising malignant oval to spindle cells with necrosis was observed, which was positive for Bcl-2, CD99, and FLI-1, but negative for pan-cytokeratin, STAT6, and CD34." (PMID 36033527, 2022). "Furthermore, IHC analysis revealed that the Ki-67 labeling index (LI) was 30–40%, indicating highly proliferative tumor cells, and a large portion of tumor cells strongly expressed Pan-TRK, S-100, and CD34, while negative for vimentin, SOX10, and desmin." (PMID 35572973, 2022). "The postoperative pathology showed the tumor cells to be positive for chromogranin, synaptophysin, cytokeratin, CD56 (partial weak), negative for vimentin, CD117, DOG-1, CD34, S-100, SMA, desmin, and Ki-67 approximately 2%, which confirmed the diagnosis of d-NETs." (PMID 33578581, 2021). "Tumor cells are positive for S100, SOX10, and CD34 and negative for MUC4." (PMID 33526082, 2021). "The results of CD34 staining by IHC showed that the MVD levels both in IPN group and cisplatin-IPN group were notably lower than that from negative control at 4 weeks after tumor implantation, suggesting TPVE treatment down-regulated tumor angiogenesis." (PMID 33685316, 2021). "Tumor cells of case No. 2 were positive for AE1/AE3, CK7, calretinin, D2-40, focal positive for WT-1, and negative for HMB45, Melan-A, Desmin, S100, Syn, CgA, CD31, and CD34." (PMID 34248850, 2021). "Sarcomatoid carcinoma cells were partially positive for AE1/AE3 and strongly positive for vimentin, whereas all the tumor cells were negative for neuroendocrine markers and other mesenchymal markers, such as desmin, SMA, myglobin, mygenin, S-100, DOG-1, CD34, CD117, CD15, CD30, and CD20." (PMID 33761637, 2021).
tumor (continued). "Therefore, we concluded that D2 and NANOG are specifically expressed in the tumor epithelium of BCC and not in the CD34+ population of CSCs and that the expression of D2 and NANOG in CSCs drastically differs from that in the bulk of tumors." (PMID 32197405, 2020). "However, on immunohistochemistry, the tumor cells showed immunoreactivity for Melan A and SMA and were negative for PAX-8, Pan-Cytokeratin, Myogenin, CD117, CD34, CK7, PAX-8 and HMB-45." (PMID 33344317, 2020). "In our case, the tumor was positive for SMA and negative for desmin, S100, CR, and CD34." (PMID 32815307, 2020). "On the contrary, the non-CSC population (i.e., CD34− cells), which constitutes the bulk of the tumor, confirmed a high D2 and NANOG expression level at the early stages of tumorigenesis, one and two weeks following tumor induction." (PMID 32197405, 2020). "In our case, the tumor cells expressed CD31, AE1/AE3, FLi-1, and ERG and were negative for CD34." (PMID 31311568, 2019). "Of note, MLN0128 did not affect the vasculature of tumor nodules, whereas in the PD901 and combination treatment groups, CD34 (+) endothelial cells could be found scattered inside the tumor tissue." (PMID 30741922, 2019). "The tumor is negative for EMA, cytokeratin 7, cytokeratin 20, chromogranin A, synaptophysin, S-100 protein, HMB-45, desmin, SMA, EBV, CD117, DOG1, CD23, CD21, clusterin, MDM2, CD34, D240, and ERG." (PMID 31623602, 2019). "In order to ensure that the tumor infiltrating human T-cells are derived from the engrafted hematopoietic cells and not from the tumor infiltrating lymphocytes (TIL) from the tumor tissue, we labeled the human CD34+ BMC with lentiviral vectors that expressed GFP proteins." (PMID 28008146, 2017). "However, on immunohistochemical analysis, the tumor was unexpectedly positive for MUC4, but negative for desmin, S100, smooth muscle actin, CD34, and CD117." (PMID 27247823, 2016). "CD34 positive represented that vessels formed by endothelial cells, while CD34 negative and PAS positive represented VM channels formed by tumor cells or ECM and even red blood cells could be found in these channels." (PMID 26992227, 2016). "However, our data showed that PKN3 ablation had no impact on tumor angiogenesis, consistent with the previous report describing the orthotopic cancer model treated with Atu027 evaluated by CD31 or CD34 immunoreactivity." (PMID 26742562, 2016). "The tumor cells show diffuse strong expression of Factor VIII, Fli-1, INI-1, vimentin, MDM2, and CDK4, local expression of CD31, AE1/AE3, EMA and P63, and no expression of CD34, S-100, actin-sm, desmin, MyoD1, and HMB45." (PMID 26315812, 2015). "S-100, calponin, cytokeratin, factor VIII, CD34, and AFP were negative in tumor cells." (PMID 26366352, 2015). "The tumor cells are negative for desmin, α-SMA, CD34, and S-100 protein." (PMID 26090253, 2015). "The tumor cells were also negative for pan-cytokeratin (CK, 1:400; Novocastra, Newcastle, UK), S100 protein (1:2,000; Dako), CD117 (1:200; Dako), CD31 (1:80; Dako), CD34 (1:400; Dako) and h-caldesmon (1:100; Dako)." (PMID 23742153, 2013). "The tumor cells were negative for α-SMA, S-100, desmin, CD34 and CD117." (PMID 23902675, 2013). "In Prostatic stromal sarcoma (PSS) unlike the PES, immunohistochemically, the tumour cells are widely positive for vimentin, CD56, CD99 and focally positive for synaptophysin, CD10, progesterone receptor, desmin and CD34, but negative for EMA, cytokeratin, estrogen receptor, S-100 and myoglobin." (PMID 23886403, 2013). "The tumor cells were negative for CD117, S100, CD34, a-SMA and desmin." (PMID 23902675, 2013).
tumor (continued). "Immunohistochemistry the tumor was positive for vimentin, smooth muscle actin and Ki-67; focal positivity with AE1-AE3 CK, CK5 and high molecular weight cytokeratin and negative for EMA, CD34, desmin, myosin, CroA, synaptophysin and S100." (PMID 23886403, 2013). "Tumor cells stained negative for CD10, CD20, CD79a, CD34, CD56, CD117, TdT, Desmin, and EMA." (PMID 22497840, 2012). "The tumor cells of the five cases were negative for SMA, desmin, CD117 and CD34." (PMID 22862905, 2012). "The lack of CD34 and CD99 expression in our case can also help to exclude this tumor." (PMID 23227905, 2012). "However, the tumor was negative for CD20, kappa and lambda light chain immunoglobulins, CD34, TDT, cytokeratin AE1/AE3, cytokeratin 5.2 and CD56." (PMID 19284608, 2009). "A tissue microarray composed of 20 normal livers, 20 cirrhotic livers, tumor and adjacent background non-neoplastic liver tissues from 20 HCC-C and 20 HCC-NC were constructed and stained immunohistochemically with antibodies against the antigen CD34." (PMID 19662192, 2007). "The tumor cells were positive for CD31 and CD34, and negative for cytokeratin." (PMID 16159405, 2005). "The resected specimen showed that the tumor contained a proliferation of spindle-shaped cells arranged in a fascicular pattern, which was immunohistochemically positive for desmin, SMA, h-caldesmon, CAM5.2, and EMA (data not shown), and negative for c-kit, AE1/AE3, CD34, and S-100 (data not shown)." (PMID 40625542, 2025). "Hence, the presence of spindle-shaped stromal cells lacking CD34 expression, and displaying CD105 expression, could potentially indicate an increased tumor aggressiveness in younger patients." (PMID 37719885, 2023). "Immunohistochemically, the staining results of tumor cells in the small intestine and kidney were consistent; the tumor cells were positive for CD3, CD56, granzyme B, TIA-1, and perforin, while negative for CD4, CD8, CD5, Desmin, CD34, CKpan, CD20, CD30, SMA, CD79ɑ, and PAX8." (PMID 36199094, 2022). "OS cells (Saos–2 cell line) downregulate the expression of angiogenic factors, such as CD34, PDGFA, PDGFRA, PDGFRB, and VEGF, in human AD-MSCs when co-cultured, implying that MSCs cannot differentiate in vitro under the induction of tumor cells and do not support tumor angiogenesis in vivo." (PMID 34681692, 2021). "The LMNA-NTRK1 fusion-positive tumor was difficult to diagnose before RNA sequencing by NGS because of its unusual pathology and immunohistochemical profile, namely, a combination of prominent inflammatory cells, no mitotic activity (0/10 HPF), and S100/CD34 coexpression." (PMID 32957984, 2020). "Transplantation of the oncogene TCL-1-transduced CD34+ cells in neonatal NSG mice did not increase the frequency of ROR1-expressing B cells, but the mouse with the highest engraftment of transduced cells developed a tumor-like lump consisting of a high percentage of ROR1-expressing B cells." (PMID 29850623, 2018). "Indeed, the body weight of nude mice is not affected by Rad51 inactivation via daily IBR2 treatment, and IBR2 has no significant inhibitory effect on CD34+ normal bone marrow cells, suggesting that inhibition of RAD51 can be tumor-selective to a certain extent." (PMID 23341130, 2013). "It was worth noting that of the 19 cases, especially in the region of the tumor-host interface where Calponin was negatively expressed, 19 (100%) cases showed FAP-a positive and 12 (63.16%) showed SMA positive, but 17 (89.47%) of these 19 cases reported negative for CD34 protein." (PMID 22067528, 2011).
tumor (continued). "Moreover, that the levels of integrated EPCs in newly formed blood vessels had been reported to be as high as 16.56% in tumor tissues, 72.24% in adjacent non-tumor tissues, and 55.86% in tumor free tissues, according to the ratio of CD133-MVD(Microvessel Density) and CD34 MVD." (PMID 21152281, 2010). "The problem of antigen specificity is highlighted by the detection of CD34 antigen on lymphatic vessels, perivascular stromal cells as well as other stromal elements while this is compounded by the absence of FVIII-RA on part of the capillary endothelium in tumour tissue." (PMID 12085206, 2002). "Additionally, the tumor was negative for most immunohistochemical markers (CKAE1/AE3, p63, CD23, CD21, MUC4, NUT, CDK4, Pan-TRK, STAT6, SS18, MDM2, Desmin, S100, ERG, TLE1, Fli) and showed only weak and most probably unspecific expression of CD99, CD56, and CD34." (PMID 39519042, 2024). "Furthermore, there was no proliferation-inhibitory effect observed in human normal CD34+ hematopoietic cells from 5 independent donors in the presence of SR140333 or Aprepitant and no hemolytic toxicity in human red blood cells, indicating selective targeting of tumor cells by NK-1R antagonists." (PMID 31488714, 2019). "However, these cells did not express GFP, suggesting that they might not be derived from the TCL-1-transduced CD34+ cells, and how TCL-1 affected the interaction of the immune cells in huNSG mice and led to the development of this tumor-like lump remains to be determined." (PMID 29850623, 2018). "However, the status of refractory or relapse, LDH level, and karyotype did not significantly affect response of primary CD34+ AML cells to chidamide in combination with IDA, indicating that the combination regimen of chidamide and IDA could rapidly diminish tumor burden in a patient with R/R AML." (PMID 28814980, 2017). "CD31, CD34, and Factor VIII are typically negative, but may be positive in areas with angiosarcomatous differentiation, indicating the undifferentiated mesenchymal origin of the tumour, with occasional tendency towards differentiation to a specific type of connective tissue." (PMID 23424592, 2013).